TP53INP1 (tumor protein p53 inducible nuclear protein 1)
Diseases named in the same sentence as TP53INP1 in open-access papers (continued):
Sharing a sentence is not in itself a finding about the gene and the disease.
neuroblastoma (6 papers, 2011 to 2024). Neuroblastoma (NB) is the most common solid, extracranial childhood tumor. "The results revealed that miR-3934-5p was shown to be highly elevated in neuroblastoma tissues and cell lines and TP53INP1 as a direct target gene of miR-3934-5p." (PMID 35011335, 2021). "I-BET151 inhibits the transcription and expression of NCYM and N-Myc in neuroblastoma cells and significantly increases the mRNA and protein levels of TP53INP1, which promotes apoptosis of tumor cells." (PMID 34540687, 2021). "Statistical analysis of neuroblastoma specimens shows that low expression of nuclear protein 1 induced by tumor protein 53 (TP53INP1) in tumor tissues and high expression of N-Myc in neuroblastoma patients are closely related to poor prognosis." (PMID 34540687, 2021). "Transfection of the Kelly neuroblastoma cells with two independent TP53INP1 siRNAs led to a marked knock-down of TP53INP1 mRNA and protein expression." (PMID 24952595, 2014). "The data suggest that a low level of TP53INP1 expression in human neuroblastoma tissues can be used as a marker for poor prognosis and for therapeutic application of the BET bromodomain inhibitors in the patients." (PMID 24952595, 2014). "Real-time RT-PCR studies showed that TP53INP1 mRNA expression negatively correlated with N-Myc mRNA expression in the 201 human neuroblastoma tissues." (PMID 24952595, 2014). "In this study, using microarray gene expression data, we observed that down-regulation of N-Myc or HDAC2 reactivated the expression of TP53INP1 in neuroblastoma cells." (PMID 24952595, 2014). "Thus, the recent findings stipulated that miR-3934-5p/TP53INP1 axis appears to be a unique therapeutic target for neuroblastoma treatment." (PMID 35011335, 2021). "Moreover, low levels of TP53INP1 expression in human neuroblastoma tissues correlated with high levels of N-Myc expression and poor patient outcome, and the BET bromodomain inhibitors JQ1 and I-BET151 reduced N-Myc expression and reactivated TP53INP1 expression in neuroblastoma cells." (PMID 24952595, 2014). "Moreover, repression of TP53INP1 in human neuroblastoma tissues is a marker for poor patient prognosis, and BET bromodomain inhibitors reactivate TP53INP1 expression in cancer cells." (PMID 24952595, 2014).
osteosarcoma (6 papers, 2019 to 2025). A usually aggressive malignant bone-forming mesenchymal neoplasm, predominantly affecting adolescents and young adults. "In this study, GAS5 was found to suppress cell proliferation and accelerate cell apoptosis of DDP-resistant osteosarcoma cells by regulating miR-26b-5p/TP53INP1 axis." (PMID 37993867, 2023). "Taken together, GAS5 enhanced the sensitivity of osteosarcoma cells to DDP via GAS5/miR-26b-5p/TP53INP1 axis." (PMID 37993867, 2023). "In this study, TP53INP1 was found to be a downstream target gene of miR-26b-5p, and partly reversed the effects of miR-26b-5p on osteosarcoma cells." (PMID 37993867, 2023). "The mRNA expression of TP53INP1 in osteosarcoma cells was confirmed by quantitative reverse transcription-PCR." (PMID 33117693, 2020). "The expression of TP53INP1 was downregulated in osteosarcoma cell lines (U2OS, Saos-2, MG-63, and HOS) compared with HFF-1, hFOB1.19, and hBMSCs." (PMID 33117693, 2020). "In this study, a newly identified regulatory mechanism of the NR_027471/miR-8055/ TP53INP1 axis was systematically studied in osteosarcoma." (PMID 33117693, 2020). "TP53INP1 was suppressed in osteosarcoma cell lines compared to osteoblasts hFOB1.19." (PMID 37993867, 2023). "In addition, mir-504 promoted the growth and metastasis of human osteosarcoma via targeting TP53INP1." (PMID 34195294, 2021). "In addition, GAS5 also enhances the sensitivity of osteosarcoma cells to Cisplatin through the GAS5/miR-26b-5p/TP53INP1 axis, which may be a potential indicator for the treatment of osteosarcoma." (PMID 39015175, 2024). "Therefore, both NR_027471 and TP53INP1 appear to play tumor suppressive roles in osteosarcoma." (PMID 33117693, 2020). "Up-regulation of GAS5 contributed to the weakened malignancy in osteosarcoma cells and enhanced DDP chemoresistance by regulating miR-26b-5p/TP53INP1 axis." (PMID 37993867, 2023). "The luciferase reporter assay showed that miR-8055 could combine with the wildtype-3′UTR of TP53INP1 mRNA in osteosarcoma cells, but not with the mutant-3′UTR of TP53INP1 mRNA." (PMID 33117693, 2020).
type 2 diabetes (6 papers, 2011 to 2024). "The lower expression of TP53INP1 was associated with methylation of cg26343298, consistent with the protective role of cg26343298 methylation on type 2 diabetes and diabetic nephropathy." (PMID 39199149, 2024). "Two SNPs in TP53INP1 (rs4734295, rs6982393) were associated with AD and type 2 diabetes (T2D), indicating potential shared molecular pathways between the diseases." (PMID 33815092, 2021). "Consistently, our findings confirmed that an increased TP53INP1 transcript level may contribute to the increased risk of type 2 diabetes (betaSMR = 0.15)." (PMID 39199149, 2024). "Notably, our results suggest that cg26343298 methylation is protective against type 2 diabetes and diabetic nephropathy, and the cg26343298 methylation site negatively regulates TP53INP1 expression, indicating a correlation between DNA methylation, TP53INP1 expression, and diabetes risk." (PMID 39199149, 2024).
melanoma (5 papers, 2011 to 2025). A malignant, usually aggressive tumor composed of atypical, neoplastic melanocytes. "We identified four genes, PPP1R3C, ENC1, RARRES1 and TP53INP1 that were not previously known to be silenced by DNA methylation in melanoma." (PMID 22028813, 2011).
Obesity (5 papers, 2015 to 2024). Accumulation of substantial excess body fat. "Taken together, those data show that TP53INP1-deficient mice are prone to obesity and liver complications, suggesting a role of TP53INP1 in dampening fat storage." (PMID 25828351, 2015). "In order to evaluate the impact of chronic oxidative stress in obesity predisposition of TP53INP1 KO mice, we treated the mice with NAC at the starting of HFD." (PMID 25828351, 2015). "As susceptibility to obesity and T2D in TP53INP1-deficient mice is redox-linked, we addressed the question of the cellular origin of chronic oxidative stress in these mice." (PMID 25828351, 2015). "By its action on redox status homeostasis, TP53INP1 is thus a new molecular actor of obesity prevention, and the current work thus adds to the knowledge of the molecular events involved in obesity predisposition." (PMID 25828351, 2015). "Use of an antioxidant treatment, which alleviates the chronic oxidative stress affecting TP53INP1-deficient animals, completely abolishes the predisposition to obesity, demonstrating that oxidative stress is the cause of exacerbated obesity in these animals." (PMID 25828351, 2015). "This suggests that TP53INP1 expression is induced as part of an obesity-associated stress response and that this protective function is lacking in TP53INP1-deficient mice, thus impairing fat homeostasis." (PMID 25828351, 2015). "Therefore, TP53INP1 mutant mice constitute an original model in which to study the implication of oxidative stress and autophagy in the development of obesity and T2D, two crucial public health issues." (PMID 25828351, 2015). "Taken together, these data lead us to state that despite skeletal muscle is considered to play an important role in the development of metabolic syndrome, this tissue would not be involved in the ROS‐drive obesity and insulin development induced by TP53INP1 deficiency." (PMID 31124296, 2019). "We can conclude from these experiments that chronic oxidative stress observed in TP53INP1-deficient cells is at the origin of the accumulation of LD, which are likely involved in the in vivo increased fat depot and hepatic steatosis associated with HFD-induced obesity." (PMID 25828351, 2015). "Finally, it is interesting to note that the TP53INP1 paralog TP53INP2 (also known as DOR for diabetes and obesity related) is also involved in MS through its implication in autophagy." (PMID 25828351, 2015). "As a consequence, the combined effects of HFD-induced obesity and the absence of TP53INP1 led to hyperglycemia (Fig2A and C), suggesting that these mice had developed T2D." (PMID 25828351, 2015). "Nonetheless, in our mouse model, the absence of TP53INP1 favors increased body weight and fat mass, most spectacularly in an experimental setting of obesity induced by lipid-rich diet." (PMID 25828351, 2015). "Interestingly, glycemia of CTRL-fed TP53INP1-deficient mice follows the same curve as HFD-fed WT mice, suggesting that absence of TP53INP1 by itself favors IR usually related to obesity." (PMID 25828351, 2015).
colon cancer (4 papers, 2020 to 2025). "FA-loaded polymeric mixed micelles will overcome its poor solubility and test colon cancer antitumor with miRNA-221/TP53INP1 axis-mediated autophagy." (PMID 40325268, 2025). "Our aim is to formulate polymeric mixed micelles loaded with FA to overcome its poor solubility and investigate its potential anticancer activity via miRNA-221/TP53INP1 axis-mediated autophagy in colon cancer." (PMID 38267567, 2024). "In addition, a decrease in miRNA 221 levels, an increase in the mRNA expression level of Bax and caspase-3, and gene expression of TP53INP1, all confirmed the mixed micelles' potential for targeting colon cancer via the miRNA-221/TP53INP1 axis-mediated autophagy." (PMID 40546695, 2025).
metabolic syndrome (4 papers, 2015 to 2025). A cluster of metabolic risk factors for CARDIOVASCULAR DISEASES and TYPE 2 DIABETES MELLITUS. "TP53INP1 is a stress-induced protein, which acts as a dual positive regulator of transcription and of autophagy and whose deficiency has been linked with cancer and metabolic syndrome." (PMID 33966044, 2021). "Although skeletal muscle has a predominant role in the development of metabolic syndrome, the bioenergetics and functional consequences of TP53INP1 deficiency upon this tissue remain undocumented." (PMID 31124296, 2019). "Taken together, our data provide evidence that the GWAS-identified TP53INP1 gene prevents metabolic syndrome, through a mechanism involving prevention of oxidative stress by mitochondrial homeostasis regulation." (PMID 25828351, 2015). "In conclusion, this study highlights TP53INP1 as a molecular regulator of redox-driven metabolic syndrome and provides a new preclinical mouse model for metabolic syndrome clinical research." (PMID 25828351, 2015). "Nevertheless, TP53INP1 deficiency does not affect oxidative stress level and mitochondrial pool in resting muscle, thereby indicating that this tissue is not involved in the development of metabolic syndrome previously reported in TP53INP1‐deficient mice." (PMID 31124296, 2019). "The primary objective of this study was to determine whether skeletal muscle is involved in the development of metabolic syndrome induced by TP53INP1 lacking." (PMID 31124296, 2019).
non-small cell lung carcinoma (4 papers, 2021 to 2024). A group of at least three distinct histological types of lung cancer, including non-small cell squamous cell carcinoma, adenocarcinoma, and large cell carcinoma. "Similarly, CAF-derived miR-130a mediates the chemoresistance to cisplatin in non-small cell lung cancer (NSCLC) cells and CAF-derived miR-106b promotes the resistance to gemcitabine by targeting TP53INP1 in pancreatic cancer." (PMID 34202583, 2021).
Bladder Cancer (3 papers, 2020 to 2022). "In addition, the miR-221/TP53INP1/p-ERK axis has been shown to regulate autophagy in bladder cancer." (PMID 36685879, 2022). "Moreover, miR-221/TP53INP1/p-ERK axis expression was shown to induce autophagy and reported to be positively correlated with the malignant property of bladder cancer cells." (PMID 36685879, 2022).
diabetes (3 papers, 2015 to 2024). "TP53INP1 has been identified as a potential susceptibility gene for diabetes based on previous GWAS." (PMID 39199149, 2024). "In summary, this SMR analysis explored the potential causal effects of OS-related genes on diabetes and its microvascular complications, highlighting the significant roles of TP53INP1, CHEK1, SUOX, and ICAM1 in the pathogenesis." (PMID 39199149, 2024). "Intriguingly, our data suggest that antioxidants may be of use in individuals with T2D variants at the TP53INP1 locus that affect diabetes risk." (PMID 25828351, 2015). "Interestingly, there are also decreases in miRNAs that regulate TP53INP1 in human diabetic islets, suggesting that over-expression of TP53INP1 may occur in β-cells in diabetes." (PMID 25828351, 2015).
lung adenocarcinoma (3 papers, 2021 to 2024). A carcinoma that arises from the lung and is characterized by the presence of malignant glandular epithelial cells. "In this study, we demonstrated that miR-106a promoted lung adenocarcinoma BM via directly targeting TP53INP1." (PMID 34718338, 2021). "In vitro, wound healing assays and Transwell assays demonstrated that overexpression of TP53INP1 significantly reversed the promoting effect of miR-106a on lung adenocarcinoma migration and invasion." (PMID 34718338, 2021). "Here we demonstrated that miR-106a targets tumour protein 53-induced nuclear protein 1 (TP53INP1) to promote BM in lung adenocarcinoma by regulating autophagy and EMT." (PMID 34718338, 2021). "Given the importance of TP53INP1 in cancer progression, our data revealed the function, mechanism and clinical implication of miR-106a in lung adenocarcinoma with BM." (PMID 34718338, 2021). "Our results suggested that targeting miR-106a/TP53INP1/autophagy signalling may represent a potential therapeutic strategy for lung adenocarcinoma with BM." (PMID 34718338, 2021). "TP53INP1, IGF1 and ZMAT3 were differentially expressed in clinical samples of lung adenocarcinoma with BM, while miR-106a and TP53INP1 showed a significant negative correlation." (PMID 34718338, 2021). "Among them, there was a negative correlation between TP53INP1 and miR-106a expression in lung adenocarcinoma tissues." (PMID 34718338, 2021). "Taken together, our study suggested that miR-106a and its target gene TP53INP1 could regulate cell migration, autophagy-dependent cell death and EMT, affecting lung adenocarcinoma BM." (PMID 34718338, 2021). "In particular, we confirmed that TP53INP1-mediated autophagy-dependent cell death and EMT could be responsible for the pro-metastatic role of miR-106a in lung adenocarcinoma." (PMID 34718338, 2021).
breast tumors (2 papers, 2011 to 2025). "Our results revealed that the TP53INP1 gene is amplified in approximately 23% of cancer cell lines and 16% of breast tumors." (PMID 41345520, 2025). "Thus, examples such as TP53INP1 would fit a potential context-dependent tumour-promoting role of miR-34a in a subset of breast tumours in vivo." (PMID 22102859, 2011). "Although, our analysis revealed that the TP53INP1 gene is amplified in about 23% of BC cell lines and 16% of tumor samples, our further analysis confirmed that this increase mostly occurs in luminal A and B subtypes of breast tumors compared to normal breast tissue." (PMID 41345520, 2025). "Additionally, unlike other subtypes of breast tumors, TP53INP1 expression in TNBC tumors, though not statistically significant, tends to be lower compared to healthy controls which may support its tumor-suppressive role in TNBC cells." (PMID 41345520, 2025).
Cerebral ischemia (2 papers, 2021 to 2025). Restriction of arterial blood supply to the brain associated with insufficient oxygenation to support the metabolic requirements of the tissue. "miR-29a in astrocyte-derived extracellular vesicles inhibits cerebral ischemia-reperfusion injury through TP53INP1 and NF-κB/NLRP3." (PMID 34220338, 2021). "Additionally, miR-29a-3p in astrocyte-derived extracellular vesicles has been found to mitigate cerebral ischemia-reperfusion injury by downregulating TP53INP1 and the NF-κB/NLRP3 signaling pathway." (PMID 40529227, 2025).
heart failure (2 papers, 2019 to 2020). Inability of the heart to pump blood at an adequate rate to meet tissue metabolic requirements. "For example miR-221 is elevated in heart failure patients and the upregulation of miR-221 exerts a protective effect in hypoxia-reoxygenation injury via targeting on Ddit4 and Tp53inp1." (PMID 30934671, 2019). "Previous studies have revealed that miR-221 inhibits autophagy and promotes heart failure by modulating the p27/CDK2/mTOR axis and inhibits hypoxia/reoxygenation-induced autophagy through the DDIT4/mTORC1 and TP53INP1/p62 pathways." (PMID 32477928, 2020).
oral cancer (2 papers, 2022 to 2024). "In addition, many studies have confirmed that miR-155 upregulation may directly contribute to chemotherapy resistance to 5-FU and Cisplatin among oral cancers through additional pathway modulation, such as TP53INP1." (PMID 38396844, 2024). "Several authors reported that miR-155-5p promotes the progression and surveillance of oral cancer by modulation of different targets such as the chromatin remodeling gene ARID2 and TP53INP1 that confirms resistance to 5-Fluorouracil." (PMID 36531016, 2022).